BRCA2 (BRCA2 DNA repair associated)
Diseases named in the same sentence as BRCA2 in open-access papers (continued):
Sharing a sentence is not in itself a finding about the gene and the disease.
ovarian carcinoma (continued). "The identification of high penetrance alleles of the BRCA1 (MIM 113705) and BRCA2 (MIM 600185) genes, which determine a high risk of developing hereditary breast and ovarian cancer, has made genetic testing an integral part of oncogenetic counseling in clinical practice." (PMID 24281179, 2010). "Identification of BRCA1 and BRCA2 has improved clinical management of some individuals with hereditary breast and ovarian cancer, but personalized care is not yet available for mutation carriers." (PMID 21037853, 2010). "One ovarian cancer patient with the PALB2 mutation had also a germline nonsense mutation of the BRCA2 gene." (PMID 20122277, 2010). "Examples of these genes are BRCA1 and BRCA2 in breast and ovarian cancers." (PMID 20111735, 2010). "The increased risk of ovarian cancer was evident only for the relatives of known BRCA1 mutation carriers, and the increased risk of prostate cancer was evident only for the relatives of known BRCA2 mutation carriers." (PMID 20877337, 2010). "Moreover, the literature also suggests that PPP1CB is a discriminator gene between BRCA1-mutant and BRCA2-mutant tumors for both breast and ovarian cancers." (PMID 19695104, 2009). "Ovarian cancers (OC) were more often found in BRCA1 families compared with BRCA2 families." (PMID 18783588, 2008). "For example, patients with non-functional (mutated) BRCA1 or BRCA2, associated with hereditary breast and ovarian cancer, respond better to platinum chemotherapy owing to an increased sensitivity to DNA damage-induced cell death." (PMID 18349819, 2008). "With regard to familial cancer phenotype this relatively small cohort does not allow for the uncovering of subtle differences between the BRCA1/2 mutant families, except for the double incidence rate of ovarian cancers in BRCA1 compared to BRCA2 positive families as reported widely before." (PMID 18783588, 2008). "Indeed a recent review in a prestige journal quoted "headline" risks for BRCA2 of only 40% and 8% for breast and ovarian cancer to 80 years." (PMID 18513387, 2008). "Notably, over 80% of ovarian cancers exhibit loss of BRCA1 and/or BRCA2 function, leading to compromised DNA repair." (PMID 18923710, 2008). "To exclude the possibility of missed BRCA1 mutations among non-BRCA1/BRCA2 families, we conducted the same analysis after excluding families with ovarian cancer cases, but this did not alter the results." (PMID 18275599, 2008). "One of the cases with a BRCA2 mutation reported a first-degree relative with prostate cancer, but neither reported a family history of breast or ovarian cancer." (PMID 17700570, 2007). "In people who do not have BRCA1 or BRCA2 gene mutations, the encoded proteins prevent breast/ovarian cancer." (PMID 17683622, 2007). "By comparison, when HPC families that include members with a history of breast or ovarian cancer are screened for BRCA2 mutations, no excess of protein-truncating BRCA2 mutations is found." (PMID 17700570, 2007). "All our BRCA2 positive cases showed a positive family history for breast and/or ovarian cancer." (PMID 16764716, 2006).
ovarian carcinoma (continued). "Risk estimates were not markedly different when women with a first primary diagnosis of ovarian cancer were excluded, with a RR (95% CI) for the ≥ 28 CAG cut-point of 0.85 (0.49–1.47) for BRCA1 mutation carriers (P = 0.6), and 1.12 (0.0.55–2.27) for BRCA2 mutation carriers (P = 0.8)." (PMID 15743497, 2005). "The HH genotype of the non-conservative amino acid substitution polymorphism N372H in the BRCA2 gene was reported to be associated with a 1.3-fold to 1.5-fold increase in the risk of both breast and ovarian cancer, but there have been negative studies as well." (PMID 16280055, 2005). "Further, BRCA2 mutations have demonstrated to have no significant occurrence in inherited epithelial ovarian cancer in Norway." (PMID 15477862, 2004). "Second, the later study also includes 42 BRCA2 carriers (43%), while the incidence in our series is established for BRCA1 carriers who have a higher intrinsic ovarian cancer risk, and this may also be true for PPSC." (PMID 15083174, 2004). "First, the same set of genes that distinguished BRCA1 and BRCA2-associated tumors also segregated the sporadic (not BRCA1 or BRCA2-associated) ovarian cancers into 2 subgroups consisting of "BRCA1-like" and "BRCA2-like" gene expression profiles." (PMID 15383145, 2004). "Of all ovarian cancers, 5% to 10% are hereditary, and most of these (65% to 75%) belong to the hereditary breast-ovarian cancer syndrome group that is linked to mutations in BRCA1 or BRCA2 tumour suppressor genes." (PMID 15345077, 2004). "Given the proportion of all breast/ovarian cancer families in our population attributable to recurring mutations, a cost-effective stepwise molecular screening strategy of BRCA1 and BRCA2 may be applied in the future." (PMID 15026808, 2004). "Overall, 31% of ovarian cancer patients and 36% of control women carried one of the two common founder mutations of BRCA1 (185 del AG or 5382 ins C) or the single common founder mutation of BRCA2 (6174 del T)." (PMID 15545966, 2004). "In a more recent analysis of 164 BRCA2 mutation-bearing families, 23.8% of tumours were ovarian (and 76.2% breast) among families with OCCR mutations: for families with mutations 5′ and 3′ of the OCCR, 8.8 and 9.6%, respectively, were ovarian cancers." (PMID 12698193, 2003). "To date, two breast and ovarian cancer predisposing genes have been identified – BRCA1, and BRCA2." (PMID 11857010, 2002). "Furthermore, women with genetic mutations in the BRCA1- and BRCA2-associated hereditary breast and ovarian cancer (HBOC) syndrome at risk of developing breast and ovarian cancer opt for oocyte cryopreservation prior to a prophylactic oophorectomy at an early age." (PMID 41528507, 2026). "Moreover, the Spanish Society of Medical Oncology clinical guidelines for ovarian cancer indicate that PARPis induce cell death in HRRD-positive tumor cells through a “synthetic lethality” mechanism, with BRCA1 and BRCA2 mutations being one of the established causes of HRRD in tumors." (PMID 41223417, 2025). "It provides further evidence that BRCA2 splicing may be regulated by factors outside the BRCA2 gene, and that a loss of coordinated splicing and BRCA2 expression by SNRPB depletion suppresses ovarian cancer cell proliferation and rescues chemotherapy response." (PMID 40724944, 2025). "Although emerging evidence suggests that the location of mutations may influence clinical outcomes, no discernible pattern has been observed indicating which location of the BRCA1/2 mutation influences clinical outcomes in ovarian cancer patients with BRCA1 and BRCA2 mutations." (PMID 40427158, 2025).
ovarian carcinoma (continued). "Furthermore, a subsequently diagnosed high-grade ovarian cancer is currently successfully undergoing targeted therapy with PARP-inhibitor olaparib, based on genetic testing results revealing interstitial loss harboring BRCA2." (PMID 39820556, 2025). "However, not all cases of HBOC can be attributed to BRCA1 and BRCA2, as more than 20 other genes have been associated with an increased risk of familial breast and/or ovarian cancer." (PMID 40648909, 2025). "Indeed, because of that, one can create the risk function for patients (with or without BRCA1/BRCA2 mutations) related to their age only and assess the risk of breast or ovarian cancer for individuals." (PMID 38279352, 2024). "Furthermore, we identified c.8187G>T as a characteristic mutation of BRCA2 in the Chinese population, and the CHEK2 mutation was significantly associated with the early onset of ovarian cancer, while the CDH1 and FAM175A mutations were more prevalent in Northeast China." (PMID 38817903, 2024). "If PARP inhibitors can promote canonical Wnt/β-catenin signaling by increasing the levels of the Wnt3A ligand, then the diminished responsiveness to canonical Wnt signaling in BRCA2-null ovarian cancer cells may also possibly contribute to the improved survival observed in BRCA2-mutant patients." (PMID 39028933, 2024). "While genetic factors are known to play a significant role in their development, specifically mutations in the breast cancer 1 (BRCA1) and breast cancer 2 (BRCA2) genes, it is important to note that not all breast and ovarian cancer patients carry these specific mutations." (PMID 38660159, 2024). "Nonetheless, it can also be considered that the presence of these truncated Tcf1/7 proteins may be the mechanism preventing the transcription of full-length Tcf1/7, Myc, and cyclin D1 and the preferential transcription of Axin2 instead in the BRCA2-null ovarian cancer cells." (PMID 39028933, 2024). "We then utilized a curated human ovarian cancer Tissue Microarray (TMA), containing WT, BRCA1-mutated, and BRCA2-mutated ovarian serous carcinoma sections to test whether the RAD18-dependent fork recovery pathway is upregulated in BRCA1 mutant tumors by immunohistochemical (IHC) analysis." (PMID 38943334, 2024). "However, the BCCRs and OCCRs never overlapped, and they concluded that breast and ovarian cancer risks varied according to the type and location of BRCA2 mutations." (PMID 37956396, 2024). "However, it is important not to forget that BRCA1 and BRCA2 mutations are not very common, representing only a small fraction of the overall burden of ovarian cancer." (PMID 38391958, 2024). "This shift value, in our understanding, represents the difference in the time of cancer occurrence; therefore, this means that patients with BRCA1/BRCA2 mutations are diagnosed with breast or ovary cancer approximately two years earlier than patients without such mutations." (PMID 38279352, 2024). "The cancer risks and spectra appear to differ between BRCA1 and BRCA2 carriers; specifically, the risk for ovarian cancer in BRCA1 carriers is higher than BRCA2 carriers, and the risks for pancreatic and prostate cancers in BRCA2 carriers may be higher than BRCA1 carriers." (PMID 36861435, 2023). "Finally, germline mutations in Breast Cancer Gene 1 (BRCA1), Breast Cancer Gene 2 (BRCA2), BRCA1 interacting Protein 1 (BRP1), Partner and Localizer of BRCA2 (PALB2), RAD51 homolog C (RAD51C), RAD51 homolog D (RAD51D), and individuals with Lynch syndrome are susceptible to ovarian cancers." (PMID 37110218, 2023). "Additionally, testing the BRCA2 mutation could guide doctors to use rucaparib (a type of poly ADP-ribose polymerase inhibitor, PARPi) for the treatment of patients with advanced ovarian cancer and metastatic castration-resistant prostate cancer." (PMID 37274233, 2023).
ovarian carcinoma (continued). "Notably, their selection included patients from families affected by breast and ovarian cancer without a germline BRCA1 or BRCA2 mutation, while our selection was focused on the presence of tumor BRCA1 promoter hypermethylation." (PMID 36112334, 2023). "Consistently, a retrospective case-control analysis of ovarian cancer patients enrolled in the ARIEL2 and ARIEL3 trials suggested an increased incidence of tMN among patients carrying pathogenic variants in genes involved in homologous recombination pathway (BRCA1, BRCA2, RAD51C and RAD51D)." (PMID 37119509, 2023). "Additionally, our study demonstrated that relatives of BRCA1 carriers have a significantly higher risk for ovarian cancer (RR = 4.72) than relatives of BRCA2 carriers, suggesting that relatives of BRCA1 carriers should be more aware of ovarian cancer than BRCA2 carriers." (PMID 36861435, 2023). "The genes that were most frequently reported in recent subgroup MINAS reports, after BRCA1 and BRCA2, included CHEK2, ATM and FANCM, which would be consistent with these ‘newer’ breast CSGs increasingly being included in gene testing panels for breast/ovarian cancer susceptibility." (PMID 34983940, 2022). "For risk reduction of ovarian cancer in this population, NCCN guidelines recommend risk-reducing salpingo-oophorectomy (RRSO), typically between age 35–40 and after completion of childbearing, noting that it is reasonable to delay RRSO until age 40–45 among BRCA2 PV carriers." (PMID 36497436, 2022). "Among the 18 women with ovarian cancer and a BRCA1 or BRCA2 mutation, ten reported a first- or second-degree relative with breast or ovarian cancer (55.5%), and there was only a slight difference between BRCA1 and BRCA2 carriers (54.5% vs. 57.1%, respectively)." (PMID 35382848, 2022). "Moreover, BRCA1 or BRCA2 mutations and a familial history of conditions such as hereditary nonpolyposis colorectal cancer also increase the risk of ovarian cancer; therefore, BRCA genetic testing is recommended for all ovarian cancer patients." (PMID 36312861, 2022). "Whether it is effective for the prevention of ovarian cancer or BRCA2 mutation carriers is not known." (PMID 35418083, 2022). "The aim of this study was to define the prevalence and spectrum of BRCA1 and BRCA2 mutations in unselected ovarian cancer patients from the Region of Podkarpacie with the use of NGS, and establish an optimal algorithm for genetic testing of women diagnosed with ovarian cancer from this region." (PMID 35382848, 2022). "Breast and gynecological cancers, such as ovarian cancer, share common genetic and non-genetic risk factors including mutations in BRCA1 and BRCA2, the most significant risk factors for both cancers, suggesting that similar biological mechanisms drive breast and ovarian cancer development." (PMID 35011637, 2021). "In addition, the mutation frequencies of BRCA2 and CDK12 were significantly higher in the C2 subtype than in the other two subtypes, suggesting that mutation of DNA repair-related genes significantly affects the prognosis of ovarian cancer patients." (PMID 34222009, 2021). "Data from this study reveal that BRCA 1 or BRCA2 variants in the non-European population is highly specific; therefore, population-specific study is essential for clinical application of treatment or prevention for breast or ovarian cancer." (PMID 34063308, 2021). "Germline BRCA1 and BRCA2 PSVs may be prevalent in up to 20% of epithelial ovarian cancer." (PMID 34930165, 2021). "Germline BRCA1 variants are often associated with young-onset life-limiting grade 3 triple-negative breast cancers, whereas for women ≥60 years with no previous cancer history who develop an epithelial ovarian cancer, BRCA2 variants are more frequently detected." (PMID 34866136, 2021).
ovarian carcinoma (continued). "In the UK, diagnostic germline genetic testing of the BRCA1/BRCA2 (hereafter BRCA1/2) genes is routinely offered through the National Health Service (NHS) to patients with a personal history (and in some cases a wider family history) of breast and/or epithelial ovarian cancer." (PMID 33654310, 2021). "And although ovarian cancer has a high hereditary portion, the frequency of genetic risk factors such as hereditary non-polyposis colorectal cancer (HNPCC)/or Lynch syndrome, BRCA1 and BRCA2 mutant genes are unknown." (PMID 32499531, 2020). "Some authors explained the contradictory results, arguing that breast and ovarian cancers have an earlier onset in BRCA1/BRCA2 mutation carriers, therefore patients might not have time to develop GC afterwards." (PMID 33198203, 2020). "Our study also revealed that BRCA2 somatic variant might contribute to the development of nonserous ovarian cancer except MC." (PMID 32813918, 2020). "In addition, BRCA1/BRCA2 gene test was not covered by health insurance as a companion diagnostic test for PARP inhibitor administration for ovarian cancer in Japan, so we did not perform it in our two cases." (PMID 33300090, 2020). "Deletion of C-terminal region of BRCA2 or mutants like BRCA2 6174delT and 6158insT impair the RAD51- binding activity of this domain, diminish the RAD51 recruitment to the damage site, and thereby increase the risk of tumor incidence in mice and early onset of breast and ovarian cancers in human." (PMID 33013205, 2020). "In the absence of BRCA1 or BRCA2 protein function, the preferential use of error-prone DNA repair mechanisms leads to genomic instability, a peculiar feature of breast and ovarian cancers arising from BRCA mutations that may favor carcinogenesis." (PMID 32481735, 2020). "In this study 489 women with a BRCA1 or BRCA2 mutation aged from 25 to 65 years, who had never had breast or ovarian cancer, were screened annually with breast magnetic resonance imaging (MRI) in addition to mammography and were followed for an average of 13 years (range: 9 to 23 years)." (PMID 33238387, 2020). "Indeed, BRCA1 and BRCA2 are the most common genes related to hereditary breast and ovarian cancers." (PMID 31412890, 2019). "Notably, a recent study identified BRCA1, but not BRCA2, mutations to be associated with immunogenic phenotype in ovarian cancers." (PMID 31022191, 2019). "The whole study design initialized with the determination of 752 miRNA levels in 59 samples (first stage of the study): (i) control (n = 16), (ii) ovarian cancer with no BRCA1/2 mutation (-/-) (n = 33) and (iii) ovarian cancer with BRCA1 or BRCA2 mutation (+/+) (n = 10)." (PMID 31465488, 2019). "Furthermore, we show in the ovarian cancer cohort how this has prognostic implication, superseding what could be derived from gene-based biomarkers (i.e. if only BRCA1 and BRCA2 mutation status were considered)." (PMID 30794536, 2019). "However, other studies found increased numbers of CD3- and CD8-positive TILs in BRCA1/2-mutated ovarian cancer without significant difference between BRCA1 or BRCA2 mutations." (PMID 31549213, 2019). "This could be supported by the fact that BRCA2 mutation carriers in the surveillance group show more other cancers (i.e., no BC or ovarian cancer) than those in the BRRM group (9% vs. 6%, P = 0.048)." (PMID 31302855, 2019). "We have found that the ovarian cancer risk modifier SNP rs34259 may have a positive impact on UNG enzyme performance and is associated with lower oxidative levels in BRCA2 carriers, which may explain the cancer‐protective effect attributed to this SNP in this group." (PMID 30747491, 2019). "In germline mutation carriers, no BRCA2 methylated ovarian cancer has been detected so far." (PMID 31225507, 2019).